STK39 (serine/threonine kinase 39)
Diseases named in the same sentence as STK39 in open-access papers (continued):
Sharing a sentence is not in itself a finding about the gene and the disease.
osteosarcoma (8 papers, 2018 to 2024). A usually aggressive malignant bone-forming mesenchymal neoplasm, predominantly affecting adolescents and young adults. "STK39 has also been implicated in several other cancers, including lung, osteosarcoma, and renal carcinoma." (PMID 37454130, 2023). "STK39 is also implicated in regulation of tumor cell proliferation, migration and invasion in multiple cancers, including osteosarcoma and cervical cancer 28,30,31." (PMID 34335956, 2021). "In human cancer, STK39 expression is elevated and positively correlated with the adverse tumor stage and poor prognosis in the non-small cell type lung cancer and osteosarcoma 28,29." (PMID 34335956, 2021). "STK39 knockdown exerted its inhibitory effects on the proliferation of osteosarcoma cell and RCC cells." (PMID 34281492, 2021). "STK39, a Ser/Thr kinase, has been reported to participate in the progression of multiple human cancers, such as osteosarcoma, renal cell carcinoma and non-small cell type lung cancer cells." (PMID 34281492, 2021). "The overexpression of STK39 was found in osteosarcoma and renal cell carcinoma (RCC)." (PMID 34281492, 2021). "Previous study pointed out that the levels of STK39 were promoted during the occurrence and development of osteosarcoma and suppression of STK39 could restrict the proliferation and invasiveness of osteosarcoma cells." (PMID 34519635, 2021). "Overexpression of STK39 could strengthen the proliferation and invasiveness of osteosarcoma cells." (PMID 34519635, 2021). "According to research, STK39 dysregulation affects MMP2 (matrix metallopeptidase 2) and MMP9 (matrix metallopeptidase 9), thus actively participating in osteosarcoma." (PMID 36005137, 2022).
essential hypertension (6 papers, 2013 to 2026). Hypertension that presents without an identifiable cause. "We therefore aimed to meta-analytically assess the risk prediction of STK39 three polymorphisms, rs6749447, rs35929607 and rs3754777, for primary hypertension." (PMID 27142475, 2016).
Obesity (5 papers, 2012 to 2025). Accumulation of substantial excess body fat. "Navigating syntenic regions suggests obesity candidate genes on chromosome 2 that are previously known to be associated with obesity-related diseases: MRPL33, PARD3B, ERBB4, STK39, and ZNF385B." (PMID 23253381, 2012).
Cerebral edema (3 papers, 2019 to 2023). "Serine/threonine kinase 39 (STK39), an activator of the p38 mitogen-activated protein kinase (MAPK) pathway, mediates cellular stress-activated signals, and is involved in the pathogenesis of brain edema." (PMID 36761411, 2023).
cervical cancer (3 papers, 2021 to 2023). A primary or metastatic malignant neoplasm involving the cervix. "Furthermore, in cervical cancer, STK39 significantly enhanced tumor invasion via activating the NF-κB/p38-MAPK/MMP2 signaling pathway." (PMID 37031178, 2023). "Evidence has shown that STK39 could promote cervical cancer progression via the NF-κB/p38 MAPK/MMP2 pathway." (PMID 34604044, 2021).
liver cancer (3 papers, 2021 to 2022). An epithelial or non-epithelial malignant neoplasm that arises from the liver. "Using a LINC00152 knockout approach KLC2, PHF19, and STK39 were validated as being regulated by the LINC00152 ceRNA network in liver cancer." (PMID 35563834, 2022). "However, pan-cancer analysis using TCGA dataset showed that overexpression of STK39 is mainly in liver cancer (both LIHC and CHOL) and few other cancer types." (PMID 33500714, 2021). "While a pro-tumorigenic role of STK39 and PHF19 has already been proposed in human HCC, the potential function of KLC2 in liver cancer has remained elusive and was thus investigated in more detail." (PMID 35563834, 2022).
non-small cell lung carcinoma (3 papers, 2013 to 2021). A group of at least three distinct histological types of lung cancer, including non-small cell squamous cell carcinoma, adenocarcinoma, and large cell carcinoma. "Moreover, knockdown of STK39 suppressed the proliferation and invasion of non-small cell lung cancer cells by inducing the cell cycle arrest and apoptosis of these cells." (PMID 34519635, 2021).
Parkinson disease (3 papers, 2012 to 2018). A progressive degenerative disorder of the central nervous system characterized by loss of dopamine producing neurons in the substantia nigra and the presence of Lewy bodies in the substantia nigra and locus coeruleus. "The first large-scale meta-analysis of published genome-wide association studies (GWAS) in Parkinson’s disease (PD) identified 5 new genetic loci (ACMSD, STK39, MCCC1/LAMP3, SYT11, and CCDC62/HIP1R)." (PMID 24312176, 2013).
prostate carcinoma (3 papers, 2021 to 2023). A carcinoma that arises from epithelial cells of the prostate gland. "Serine/Threonine Kinase 39 (STK39) regulates osmotic stress responses, and reports have linked lower expression to treatment resistance in breast and prostate cancers." (PMID 37454130, 2023). "The progression of breast and prostate cancer also has been linked to the reduced expression of STK39, and the deletion of STK39 also has implications for B-cell lymphomas." (PMID 37627077, 2023). "The lower level of STK39 mRNA expression in patients with primary prostate cancer had a higher incidence of metastases." (PMID 34281492, 2021).
renal cell carcinoma (3 papers, 2021 to 2023). "The function of STK39 was investigated in the context of renal cell carcinoma (RCC)." (PMID 37627077, 2023).
B cell lymphomas (2 papers, 2018 to 2023). "The loss of STK39 leads to an increased cell survival despite DNA damage in B-cell lymphoma and creates a pathway for enhanced resistance in the presence of genotoxic stress." (PMID 37627077, 2023). "Interestingly, STK39 has been shown to be well expressed in naive, germinal center, and memory B cells, but its expression is silenced in B cell lymphomas, leading to the loss of SPAK expression." (PMID 29367247, 2018). "One cellular gene, STK39, was of particular interest because it has recently been reported in the literature to have a role in apoptosis activation in B cell lymphoma." (PMID 29367247, 2018). "As STK39 was recently shown to be silenced in B cell lymphoma through DNA methylation around the STK39 transcription start site, we attempted to assess the DNA methylation status of the CpG island around the STK39 TSS in LCLs." (PMID 29367247, 2018). "Considering the STK39 role in B cell lymphoma, it is tempting to speculate that silencing of STK39 in primary B cells by EBV might be an important step for the suppression of apoptosis induced after infection." (PMID 29367247, 2018). "Interestingly, it was recently shown that STK39 is silenced in B cell lymphoma through DNA hypermethylation around the STK39 transcription start site." (PMID 29367247, 2018). "Considering that EZH2 is involved in STK39 regulation and considering that a recent study showed STK39 to be repressed by DNA hypermethylation in B cell lymphoma, we assessed whether DNA methyltransferases were involved in the EBNA3A-mediated silencing of STK39 in LCLs." (PMID 29367247, 2018).
chronic kidney disease (2 papers, 2022 to 2025). Impairment of the renal function secondary to chronic kidney damage persisting for three or more months. "Among the putative human Six1 targets are also the metallophosphoesterase MPPED2, which has been associated with chronic kidney disease, and the serine/threonine kinase 39 (STK39), also called SPAK." (PMID 40213817, 2025).
Diabetes (2 papers, 2009 to 2020). "Klooster’s study showed that STK39 was associated with insulin resistance in humans, which is the key pathological process of diabetes, while Hafver’s study showed that STK39 could bind to NCX1, a sodium–calcium exchanger involved in end-stage human heart failure." (PMID 32602534, 2020).
leukaemia (2 papers, 2021 to 2025). "Targeting OXSR1 strongly suppressed the growth of MA9 leukaemia cells, in which the expression of STK39 is undetectable." (PMID 40425534, 2025). "We show that genetic depletion and pharmacological inhibition of WNK1 or its downstream phosphorylation targets OXSR1 and STK39 strongly reduce cell proliferation and induce apoptosis in leukaemia cells in vitro and in vivo." (PMID 40425534, 2025).
renal carcinoma (2 papers, 2021 to 2023). A carcinoma arising from the epithelium of the renal parenchyma or the renal pelvis. "Moreover, the study also revealed that the knockdown of STK39 suppressed the proliferation and invasion of renal carcinoma cells by restricting the phosphorylation of p38." (PMID 34519635, 2021). "Knockdown of STK39 inhibited the expression of p-p38 in HCC cells Previous research indicated that STK39 could regulate p38-related pathway and affect the development of renal carcinoma." (PMID 34519635, 2021).
status epilepticus (2 papers, 2022 to 2024). Status epilepticus is defined as a continuous seizure lasting more than 30 min, or two or more seizures without full recovery of consciousness between any of them. "Therefore, we speculate that the rs1850440-associated strong expression of STK39 predisposes children to AESD because the onset of AESD is preceded by a high fever and status epilepticus." (PMID 35079012, 2022).
COVID-19 (1 paper, 2024). A disease caused by infection with severe acute respiratory syndrome coronavirus 2. "STK39 (serine/threonine kinase 39, DCHT, PASK, SPAK) showed a strong signal in a GWAS meta-analysis of hospitalized COVID-19 patients with severe disease." (PMID 38674024, 2024). "A GWAS meta-analysis of hospitalized COVID-19 patients found a strong signal for STK39." (PMID 38674024, 2024).
gastric cancer (1 paper, 2021). A primary or metastatic malignant neoplasm involving the stomach. "Collectively, circPTK2 could induce the apoptosis of gastric cancer cells by regulating the miR-196a-3p/AATK/STK39/p39 pathways." (PMID 34604044, 2021). "The results showed that AATK could bind with STK39 in gastric cancer cell contexts." (PMID 34604044, 2021). "Our data indicated that overexpression of AATK notably downregulated the expressions of p-STK39 and p-p38 in gastric cancer cells, suggesting that AATK might inhibit gastric cancer progression via inactivating the STK39/p38 signaling pathway." (PMID 34604044, 2021).
lung carcinoma (1 paper, 2023). "In lung carcinoma, the over-expression of STK39 was associated with advanced tumor stage and poor prognosis." (PMID 37031178, 2023).
lymph node metastasis (1 paper, 2021). "Reports demonstrated that STK39 expression was significantly increased in non-small lung cancer cells, and expression was positively associated with advanced tumor staging, lymph node metastasis and poor prognosis." (PMID 34335956, 2021).
metastatic cancers (1 paper, 2021). A carcinoma which has spread from the original site of growth to another anatomic site. "Our study also has important implication for the development of STK39-based targeting strategies for metastatic cancers." (PMID 34335956, 2021).
pituitary tumor (1 paper, 2025). A benign or malignant neoplasm affecting the pituitary gland. "In the pituitary tumor cohort (GSE169498), we identified a total of five MRGs (MED27, RARRES2, AKAP8L, RAB5B, and STK39) that are associated with the invasiveness of pituitary tumors." (PMID 40873641, 2025).
retinoblastoma (1 paper, 2018). A malignant tumor that originates in the nuclear layer of the retina. "The substrates of WNK1 such as MAPK1, OXSR1, STK39 (SPAK), and ANKS1A were identified to be phosphorylated in our study, but their phosphorylation status was unchanged in retinoblastoma compared to control retina tissues." (PMID 29914080, 2018).
triple-negative breast carcinoma (1 paper, 2025). An invasive breast carcinoma which is negative for expression of estrogen receptor (ER), progesterone receptor (PR), and human epidermal growth factor receptor 2 (HER2). "The same miRNA, lb-miR-166a, was shown to directly target STK39 in triple-negative breast cancer cells, suppressing proliferation, invasion, and metastasis while promoting apoptosis through the inhibition of the STK39/MAPK14 signalling pathway." (PMID 41465116, 2025).
tumor (25 papers, 2014 to 2025). "Recent studies have shown that STK39 expression is associated with tumor malignancy in some cancers 33-35." (PMID 33500714, 2021). "A combination of Otud6b, Stk39 and Lgals8 gave an AUC of 0.868 (95% CI 0.744-0.968, p < 0.001) for pre-diagnostic sera and 0.871 for sera derived from tumor bearing mice (95% CI 0.744-0.976, p < 0.001) with a sensitivity of 0.75 and specificity of 0.8." (PMID 24886063, 2014). "Therefore, our study not only clearly confirms the role of STK39 in tumor metastasis but also reveals the underlying molecular mechanism." (PMID 34335956, 2021). "Because WNK1 activates OSR1/SPAK, if the osr1a/osr1b or stk39 are involved in tumor-induced angiogenesis, they are supposed to be upregulated from 2 dpi to 3 dpi." (PMID 36292952, 2022). "To validate the data from databases and cell lines, we quantified STK39 mRNA levels, protein and phosphorylation levels in matched normal liver tissues and tumor tissues of HCC patients by qPCR and immunoblotting." (PMID 33500714, 2021). "The results showed that both the expression and the phosphorylation levels of STK39 were significantly increased in HCC tumor tissues." (PMID 33500714, 2021). "Knockdown of STK39 suppressed the proliferation of HCC tumor in vivo In this part, we detected the effect of STK39 on the formation of HCC tumor in vivo." (PMID 34519635, 2021). "Serine/threonine kinase 39, a member of the Ste20 kinase family, plays a role in regulating the progression of tumours; silencing the expression of this kinase protein inhibits the proliferation of cells, promotes the differentiation of cells, induces apoptosis, and arrests the cell cycle." (PMID 40265380, 2025). "It was observed that STK39 exhibited overexpression in RCC tissues, leading to the hypothesis that STK39 may hinder apoptosis to facilitate tumor growth." (PMID 37627077, 2023). "Serine/threonine kinase 39 (STK39) has been found to function as a tumor oncogene in human cancers." (PMID 34604044, 2021). "STK39 expression was increased in HCC tumor tissues compared with normal liver tissues." (PMID 33500714, 2021). "Results showed that the knockdown of STK39 restricted the growth of HCC tumor in vivo." (PMID 34519635, 2021). "Furthermore, the high expression of STK39 is correlated with advanced tumor pathological stage, low OS and DFS." (PMID 34281492, 2021). "Similarly, the phosphorylation of ERK1/2 in tumor xenografts, generated from subcutaneous inoculation of STK39-knockdown HuH7 cells, declined significantly." (PMID 33500714, 2021). "Consistently, knockdown of STK39 inhibited the HCC tumor growth in vivo." (PMID 34519635, 2021). "To clarify the potential role of STK39 in HCC, the expression of STK39 between matched normal liver tissues and tumor tissues of HCC patients was analyzed, and we observed that STK39 expression was markedly upregulated in HCC tumor tissues (about 62.5% patients with overexpressed STK39)." (PMID 33500714, 2021). "In tumor bearing mice, IgG autoantibody incidence ranged from 5% (Pdhx, Stk39) to 50% (Lgals8)." (PMID 24886063, 2014). "IgM responses were found in 0% (Pdhx, Lgals8) to 20% (Stk39) of tumor bearing mice." (PMID 24886063, 2014). "Moreover, lower levels of STK39 also suppressed the proliferation of HCC tumor in vivo." (PMID 34519635, 2021). "In addition, STK39 plays a critical role in tumor metastasis." (PMID 34335956, 2021). "In addition, depletion of STK39 impacts tumor cell sensitivity to chemotherapeutic agents." (PMID 34335956, 2021). "SCAMP3 level was positively correlated with disease stages and tumor grades and negatively correlated with patient survival; SOX4, STK39, TARBP1, and TDRKH can be regarded as potential prognosticators and therapeutic targets for HCC." (PMID 34277395, 2021). "In summary, our study unveils a mechanism by which STK39 promotes EMT and the metastasis of tumor cells by enhancing the stability of SNAI1." (PMID 34335956, 2021).
tumor (continued). "Functionally, STK39 inhibition markedly impaired the EMT phenotype and decreased tumor cell migration, invasion, and metastasis both in vitro and in vivo." (PMID 34335956, 2021). "Thus, we considered that CDKN2B-AS1 regulated tumor progression of MCF7 and T47D cells through miR-122-5p/STK39 axis." (PMID 34374638, 2021). "Consistent with these, Immunohistochemical (IHC) staining assay confirmed that STK39 expression was elevated in HCC tumor tissues compared to normal liver tissues." (PMID 33500714, 2021). "For detecting the level of Ki67 and STK39, sh-CDKN2B-AS1 lowered both the expression in tumor." (PMID 34374638, 2021). "The tumor volume and weight of STK39 knockdown group was lower than those of negative control group (p < 0.01)." (PMID 34519635, 2021). "In one study using TgMMTV-neu mouse, three early-stage tumor antigens (PDHX, STK39, and OTUD6B) were identified by serological analysis of cDNA expression libraries (SEREX) screen that could serve as superior antigen targets for the inhibition of tumor growth." (PMID 37513965, 2023). "Furthermore, results of immunohistochemistry showed that the expression levels of Ki-67, MMP-2 and STK39 in tumor of STK39 knockdown group were lower than that in negative control group (p < 0.01)." (PMID 34519635, 2021).